TNF (tumor necrosis factor)
Diseases named in the same sentence as TNF in open-access papers (continued):
Sharing a sentence is not in itself a finding about the gene and the disease.
infection (continued). "It is also likely that cytokines may only play a dominant role in some aspects of THEV-infection, such as the clinical hemorrhage of the intestines but not the associated IMS since a study using the TNF-blocking drug (thalidomide) only prevented intestinal disease, not IMS." (PMID 40143230, 2025). "TNF-α and IFN-γ were highly expressed in C11_terminal effector CD8+ - 1 and C14_terminal effector CD8+ - 2 in both groups, indicating that these two clusters played an important role in the early stages of infection but may gradually decrease or disappear afterward." (PMID 40242765, 2025). "However, IFN-γ, IL-2, and TNF-α levels and vaccine-specific antibody concentrations in the plasma were significantly elevated in the rEg.P29T+B + CpG + infection and rEg.P29 + CpG + infection groups compared to those in the PBS + infection and CpG + infection groups." (PMID 40266142, 2025). "TNF may then activate endothelial cells by promoting the expression of adhesion molecules like intercellular adhesion molecule 1 (ICAM-1), vascular cell adhesion molecule 1 (VCAM-1), and the secretion of chemokines that attract immune cells to the site of infection." (PMID 40283058, 2025). "The increase in TNF-α levels may be related to an increase in the inflammatory response induced by the infection and suggests that the CBD supplement, rather than having an immunosuppressive effect, may have increased the inflammatory response in the context of this infection." (PMID 40356900, 2025). "Therefore, to verify the functional consequences of synergistic induction of PGE2 by oral bacteria and TNF in GFs, we established an experimental system where conditioned media from GFs subjected to infection with F. nucleatum in the presence or absence of TNF were used as a stimulus for MDMs." (PMID 40178270, 2025). "Notably, administration of oxytocin has been shown to upregulate pro-inflammatory cytokines, including interleukin-6 and tumor necrosis factor-α, through activation of peripheral mononuclear cells, thereby contributing to maternal hyperthermia even in the absence of infection." (PMID 41040641, 2025). "Although grn expression was low and not significantly different between WT and TNF KO granulocytes during craniotomy infection, it is possible that other cell types are a source of PGRN, which could be pursued in future studies that are outside the scope of the current report." (PMID 39044282, 2024). "In terms of the lethal infection model of neonatal mice by HTNV57, treatment with clophosome or the TNFα neutralizing antibody at the early stage (namely 1 day post infection/dpi), but not the progressive stage (namely 5 dpi), could effectively improve the disease outcome." (PMID 38200007, 2024). "Similarly, we show that in the absence of STING at late times post-infection, there are higher TNFα levels and reduced Il-1ra induction as compared to control cells, suggesting that STING might have a role in the progression to chronic infection." (PMID 38459007, 2024). "Overall, the ability of pantethine to reduce the infection-induced increases in MAVS, IRF3 and STING expression could explain the antiviral and anti-inflammatory effects of pantethine, which significantly inhibited IFNβ, TNFα and IL6 expression in infected Calu-3a cells." (PMID 36754974, 2023). "It has been shown previously and in the present study that transcriptions of TNF, CXCL8, and CXCL10 in hBECs were induced upon A. fumigatus infection, which could help recruit neutrophils, phagocytes, and/or other immune cells to the sites of infection for fungal clearance." (PMID 37695039, 2023). "In addition, the same was held with SVCV infection, we found that bazedoxifene/Stattic/17-AAG/AUY922/PGE2/VPA treatment inhibits or increases the SVCV genome entry, and the transcription of pro-inflammatory cytokines (IL6, TNF-α, IL1β) accordingly in a dose-dependent manner." (PMID 37099596, 2023).
infection (continued). "Therefore, the presence of elevated levels of TNF-α and the increase of lymphocytes T CD4+ in patients under DMARDs treatment could suggest a relation between the poor response to treatment and the infection by protozoa, even though more robust studies are required to delve into this aspect." (PMID 35492365, 2022). "Therefore, O. tsutsugamushi infection promoted TNF-α protein production and induced differential expression profiles of TNFR1 and TNFR2 on innate versus adaptive immune cells, in a comparable manner between a lymphoid organ (spleen) and a major organ of infection (lung)." (PMID 35479068, 2022). "In addition, iNOS transcript level was significantly downregulated in anti-TNF-α-treated mice, indicating that iNOS, which may contribute to bacterium killing, was highly dependent on TNF signals at both the early and late stages of infection." (PMID 35479068, 2022). "In addition, we also found that the mRNA transcript levels of pro-inflammatory cytokines IL-1β, TNF-α, IL-6, and IL-12, and anti-inflammatory cytokines IL-4, and IL-10 tended to decrease (p < 0.05 or p < 0.01) in the cats from the feIFN-ω’ treatment group, compared with the FPV infection group." (PMID 35068319, 2022). "However, infection of alveolar epithelial cells and alveolar macrophages with SARS-CoV-2 results in these cells producing markedly elevated levels of cytokines or chemokines such as IL-6, IL-8, tumor necrosis factor (TNF)-α, and C-X-C motif chemokine ligand 8 (CXCL8), resulting in a cytokine storm." (PMID 35328761, 2022). "Thus, the significantly decreased TNF-α production in the present study might be explained by the fact that H9N2 virus preceding 7-day infection limited the ability of alveolar macrophages to produce TNF-α without impacting pneumococcal clearance." (PMID 33722928, 2021). "Interestingly, after exposure to BECs, regardless of infection or TNF-α treatment, both CD16+ and CD16– monocytes lost their CD62L expression, possible due to binding with CD34, the endothelial cell ligand for CD62L, and subsequent cleaving and/or internalization." (PMID 33690725, 2021). "In addition, the median fluorescence intensity (MFI) of TIGIT+NK cells that expressed TNF-α, CD107a, and IFN-γ was significantly weaker than that of TIGIT−NK cells (all P < 0.05) in both HIV-1-negative donors and HIV-1-infected individuals at different stages of infection." (PMID 33717085, 2021). "Remarkably, we found higher TNF, IL-1β, IL-6, and IL-10 in lung homogenates of LysM-cre × Hif1αfl/fl mice when compared with Hif1αfl/fl control mice at 12 hours after inoculation, but these differences in pulmonary cytokine levels were not present after 40 hours of infection." (PMID 34393650, 2021). "From the two indigenous genotypes (D and G), infection with genotype D did not release any of the inflammatory cytokines as compared to that of the other genotypes whereas infection with genotype G showed significantly higher TNF-α IL-6, IL-8, IP-10 production in infected neuronal cells." (PMID 34493781, 2021). "Indeed, stimulation with Mtb antigens Early Secretory Antigenic Target (ESAT)-6 and Culture Filtrate Protein (CFP)-10 induces IFN-γ and TNF-α production by the CD4+ and CD8+T cells that may provide tools to study the role of these early responses in protection from a fatal infection." (PMID 34484203, 2021). "While reading mechanisms of infection and immune responses against CMV and M. tuberculosis, we might recall some features outlined in BMF pathogenesis, such as involvement of type I IFNs and TNFα and predominant roles of Th1 and CTLs; however, several questions might rise as well." (PMID 34805223, 2021). "No raise in IFN-γ expression was observed after heterologous infection as well as no clear change in expression for other tested cytokines could be observed, except for an approximately 5-fold increase in TNFα, IL-10 and TGF-β mRNA in some genotype B strain infected goats." (PMID 34575988, 2021).
infection (continued). "However, during EAEC infection, proinflammatory cytokines could enhance mucus secretion through enterocytes, since among the E. coli pathotypes, EAEC is the best inducer of TNF-α secretion in epithelial cells and induces the secretion of TNF-α, IL-6, or IL-1β by macrophages." (PMID 33281812, 2020). "In the context of infection by P. brasiliensis, the absence of TLR9 increases the susceptibility of mice at the beginning of the infection (48 h), generating an exacerbated inflammatory response with the increased neutrophil influx and high levels of TNF-α at the site of infection." (PMID 33194839, 2020). "IFN-γ and TNF-α were significantly reduced in the lungs of mice that had been vaccinated at either 7 or 14 days prior, compared to non-vaccinated mice that were subjected to the same infection, suggesting a non-essential role for these cytokines in BCG induced immunity." (PMID 32625209, 2020). "This set of data indicates that the T4SS might contribute to the release of inflammatory cytokines immediately post-infection in moDCs, whereas it does not play a crucial role in the secretion of IL-1β, IL-8, and TNFα and in surface marker expression at later time points." (PMID 32486097, 2020). "Mammary infection by Staph. aureus does not increase the production and release of TNF-α as does infection by Gram-negative bacteria, but it was demonstrated that Staph. aureus could increase the concentration of other cytokines that could lead to an elevated APP concentration." (PMID 32867136, 2020). "However, TNF-α and IL-1 were at best barely detected in these models, regardless of the infection." (PMID 32731452, 2020). "Interestingly, substantial down-regulation was also noted in pro-inflammatory cytokines (i.e. IFN-γ, TNF-α, IL-12, IL-2, IL-17 and iNOS), while, up-regulation of anti-inflammatory cytokines (i.e. IL-10, IL-4 and TGF-β) during asymptomatic pre-erythrocytic liver-stage infection." (PMID 32181014, 2020). "Interestingly, neither TNF-α nor IL-17 were changed in response to infection in our model." (PMID 32958528, 2020). "PAF C-16 can activate monocytes/macrophages by binding to PAFR and stimulate the production of inflammatory mediators such as TNF-α, IL-1α and β, reactive oxygen intermediate (ROI) and reactive nitrogen intermediate (RNI) species, and thus may play a protective role during infection." (PMID 32587578, 2020). "However, this is not represented in each compartment of the body, as acute alcohol use may deter TNFα production in serum, but, on the other hand, bronchoalveolar lavage fluid TNFα levels in the mouse model were not altered at any time after infection." (PMID 31739600, 2019). "However, our experiments were based on recombinant bovine TNF-α; thus, our results could not be necessarily applied to infection situations because disease progressions are mediated by more complex interactions between pathogens and host immunity." (PMID 30819151, 2019). "The TNF-α /IL-10 ratios were not significantly changed regardless of the organ, the bacteria lifestyle and the time point post-inoculation, except in the spleen of mice infected with sessile bacteria where they were significantly lower than in non-infected mice at 24 h time point after infection." (PMID 31583108, 2019). "Also TNFα, considered as an important component in the inflammatory response in fish and activated in rainbow trout after i.p. injection of live theronts of I. multifiliis, was not induced by infection." (PMID 31220151, 2019). "EV Y inoculation without infection did not stimulate the production of NO, but spleen cells from uninfected mice inoculated with EV Y and stimulated in vitro with TcAg produced lower levels of TNF-α, IFN-γ, IL-10, and IL-6 than did spleens cells from control mice." (PMID 29755471, 2018).
infection (continued). "Given that several such cytokines, such as TNF, IL‐1β, and IL‐6, are potent, nonredundant mediators of anti‐TB immunity, it is perhaps not surprising that their regulatory pathways represent attractive targets for dampening the host immune response to infection." (PMID 29345343, 2018). "We found that the percentage of CD4+ T cells producing IFNγ and TNFα were significantly reduced in the groups receiving ART plus PH-797804 compared to ART alone, whether the treatment is started on week 1 (p = 0.005 for TNFα and p = 0.02 for IFNγ) or week 6 post-infection (p = 0.04 for TNFα)." (PMID 30161247, 2018). "Similarly, neither infection nor treatment altered the levels of serum TNF or plasma IL-6." (PMID 30072754, 2018). "The associations between TNFα mRNA (P = 0.03) and subsequent infection were independent of the duration of the operation whereas the associations between IL-23 (P = 0.44), RORγt (P = 0.43), FOXP3 (P = 0.49), IL-12 (P = 0.60) and T bet (P = 0.11) mRNA and subsequent infection were not." (PMID 30212506, 2018). "However, while these observations were consistent with the purified ligand LPS they were not fully consistent in an infection setting when Listeria were used to stimulate the macrophages, though there was still a significant increase in TNF-α secretion in the miR-21−/− macrophages." (PMID 28589100, 2017). "In addition to the cell migration, the infection of microglia with P. gingivalis significantly increased the mRNA expression of proinflammatory mediators, including IL-6, TNF-α, and iNOS, without affecting the mRNA expression of anti-inflammatory mediators, including IL-10, arginase-1 and IL-4." (PMID 28924232, 2017). "Furthermore, for side effects, anti-TNF therapy could significantly increase the incidence of infection in CD rather than UC." (PMID 29228739, 2017). "In addition, previous studies have demonstrated that MSCs may participate in the mitigation of infection by secretion of soluble paracrine factors including interleukin (IL)-10, prostaglandin E2 (PGE2), tumor necrosis factor (TNF)-α-stimulated gene/protein 6, and IL-6." (PMID 28114965, 2017). "Additionally, it should be noted that even during the early onset of infection with negative DTH response (III profile) IL-6 showed significantly higher serum levels than those of TNF-α, IL-4, and IL-10, suggesting that it exerts a latent immunopathogenic effect even during early infection onset." (PMID 27051668, 2016). "Such a pathway could be amplified in the case of infections with CMV and EBV, since the viruses need live, functional and activated “lymphocytes” which could be achieved by controlling the same NF-κB signaling pathway and, in turn, by blocking TNF-related apoptosis." (PMID 27582741, 2016). "Therefore, we demonstrated that immunobiotic administration induce an early increase in the levels of TNF and IL-6 in the respiratory tract after poly(I:C), RSV, or IFV challenge, while the levels of those proinflammatory factors are significantly reduced later during infection." (PMID 28066442, 2016). "Indeed, HIV-1 expression from uDNA after infection by the HIV-1 env−gfp+ D116N virus is strongly stimulated by treatments inhibiting NF-κB activation (PDTC and DSFM treatment conditions) while it is diminished by treatments stimulating NF-κB activation (TNF-α, PRO and PHA treatment conditions)." (PMID 27167871, 2016). "A significant decrease was found in TNF-α/ IL-10 ratio [which was used as a measure of T helper (h) 1/ Th2 balance (proinflammatory and cellular immunity vs. anti-inflammatory and humoral immunity)], compared to patients without infection in the second sample (P = 0,000)." (PMID 27453748, 2016). "In order to assess whether or not early circulating plasma TNF-α/IL-10 ratio may indeed be a novel predictive biomarker for hypersusceptibility to infections, we assessed the AUROC of the various logistic models with TNF-α/IL-10, TBSA, and the various continuous severity scores." (PMID 27761434, 2016).
infection (continued). "There were minimal levels of serum IL-6, CCL2, CXCL1, and TNF-α in mice without CVB3 infection, while those infected with CVB3 had significantly increased inflammatory cytokines and chemokines on day 5 post infection, which might be associated with exacerbation of pancreatic inflammation." (PMID 27195463, 2016). "Indeed, TNF-α is an early up-regulated cytokine that is rapidly down-regulated within 4 to 6h post-infection, a time for which the level of IgA protease may not be good enough to compromise NF-κB activity and hence TNF-α expression." (PMID 26241037, 2015). "Furthermore, IL-6 and TNF-α gene induction was higher in mouse brains challenged with JEV-WT than JEV-NS5–M19A and IL-6 protein could be detected in the sera of mice with JEV-WT infection." (PMID 25816318, 2015). "Since TNF has been shown to modulate the expansion of regulatory T cell networks, the absence of TNF signaling may modify the local immune response in a way that it becomes refractory to the activity of IFN-γ and iNOS and therefore unable to prevent progressive infection." (PMID 26834705, 2015). "In summary, C. septicum strains that did not encode a functional α-toxin did not induce high levels of TNF-α release at distal sites of infection, whereas strains that produced functional toxin were able to induce TNF-α release at comparable levels to that seen in a localised area of infection." (PMID 25675415, 2015). "We found that cytokines typically of effector T cell origin (e.g. IFNγ, IL-10, and TNF) were not significantly altered in WT and KO mice, although there was a general trend toward higher cytokine levels in IL-21R KO mice late after infection (i.e. day 14 p.i.)." (PMID 25849970, 2015). "Infection at delivery, but not earlier in pregnancy, was associated with significantly higher TLR3-mediated IL-6 and IL-10 responses in the first 3 months of life, and with significantly higher TLR3-/TLR7/8-/TLR9-mediated TNF-α and TLR9-mediated IL-10 responses at 6 or 12 months of age." (PMID 26580401, 2015). "In contrast, TNFα treatment at the time of infection reduced the number of non-productively infected cells by ~2.3 fold (‘red-yellow ratio’ ~0.7), indicating that NFκB up regulation during infection largely mitigates the formation of direct non-productive infection." (PMID 24502247, 2014). "Interestingly, TNFα is absolutely required at the time of challenge infection and can be provided by either T cells or non-T cells, whereas IFNγ provided by T cells prior to challenge appears to facilitate the differentiation of optimally protective CD8 T cells." (PMID 24854422, 2014). "Furthermore, these findings collectively support the idea that non-productive RGH infection is established early (within four days post-infection) and permanently, such that TNFα treatment applied after the infection can no longer permanently alter the proportion of non-productively infected cells." (PMID 24502247, 2014). "However, TNF-α protein expression decreased about 50% in the bezafibrate, 55% in the fenofibrate, and 25% in the gemfibrozil treated groups compared with that in the non-infected vehicle control group at 1 h after infection." (PMID 25299393, 2014). "The infection state exhibits non-specific host responses, including immune responses such as changes in the concentrations of certain plasma proteins, cytokines (tumor necrosis factor, interleukin-1, interleukin-6) and interferon which may result in reduction of serum zinc level." (PMID 24353677, 2013). "Therefore, it will be important to determine whether or not specific amino acid substitutions can influence TNF-α expression and thus contribute to the pathogenesis of the lethal process during JaTH160 infection." (PMID 23940775, 2013). "Importantly, absence of TNF-α did not significantly alter the resolution of infection." (PMID 23483844, 2013).